SOCS2 (suppressor of cytokine signaling 2)
Diseases named in the same sentence as SOCS2 in open-access papers (continued):
Sharing a sentence is not in itself a finding about the gene and the disease.
mastitis (8 papers, 2017 to 2024). Inflammation of breast tissue during lactation or postpartum due to an obstructed duct or infection. "In this study, we chose the causal mutation for mastitis resistance characterized in a dairy sheep association study: namely the R96C point mutation in the SOCS2 gene (suppressor of cytokine signaling 2)." (PMID 31533617, 2019). "These genes included CCNT1, previously associated with milk and cheese-making traits; LALBA, associated with milk production traits; MRPL42, a candidate gene for mastitis resistance; and the gene suppressor of cytokine signaling 2 (SOCS2) associated with mastitis susceptibility." (PMID 39080565, 2024). "These haplotypes are located in the region of the p.R96C mutation (OAR3, g.129722200C>T, genome assembly v3.1) that has been previously detected in the suppressor of cytokine signaling 2 (SOCS2) gene in Lacaune dairy sheep and is associated with sensitivity to mastitis." (PMID 33932977, 2021). "For example, GSN has been suggested as indicator of mastitis and many studies have documented important function of SOCS2 in the regulation of cytokines and mastitis." (PMID 32754201, 2020). "The SOCS2 gene, which influences body growth, milk production and somatic cell scores, a proxy for mastitis, was studied as an example in dairy sheep." (PMID 31533617, 2019). "The result of this imputation provided us with the SOCS2 genotypes for the entire genotyped population, with a MAF of 0.14 for the mutated T allele associated with higher susceptibility to mastitis." (PMID 31533617, 2019). "The signature on chromosome 3 harbours the SOCS2 gene recently shown to carry a mutation with adverse pleiotropic effects, positive for growth and negative for mastitis." (PMID 29357834, 2018). "In this study, the frequency of the SOCS2 SNP allele was found to decrease for AI rams (from 0.21 in 2005 to 0.09 in 2017), which might be explained by the introduction of the SCS trait, considered as a proxy for mastitis, into the breeding objectives in Lacaune dairy sheep in 2005." (PMID 31533617, 2019).
acute myeloid leukemia (7 papers, 2019 to 2022). Acute myeloid leukemia (AML) is a group of neoplasms arising from precursor cells committed to the myeloid cell-line differentiation. "SOCS2 downregulation is also observed in human acute myeloid leukemia (AML) cells that carry RAS mutations." (PMID 35352806, 2022). "On the contrary, SOCS2 was elucidated as a growth promoter in acute myeloid leukemia." (PMID 33397365, 2021). "High levels of SOCS2 was identified as an adverse prognostic characteristic of acute myeloid leukemia (AML) and ALL, such as those with MLL rearrangement or BCR/ABL fusions." (PMID 31523525, 2019). "The expression of SOCS2, which was found inhibited after PLK1 inhibition by RO3280 treatment in acute myeloid leukemia cells in our previous study 42, was also down regulated in neuroblastoma cells after PLK1 blockage, suggesting the involvement of SOCS2 in PLK1 pathway." (PMID 32231733, 2020).
osteoarthritis (7 papers, 2021 to 2024). A noninflammatory degenerative joint disease occurring chiefly in older persons, characterized by degeneration of the articular cartilage, hypertrophy of bone at the margins and changes in the synovial membrane. "SOCS2 mRNA levels were decreased in osteoarthritis patients, and a polymorphism in the SOCS2 gene correlated with susceptibility to type 2 diabetes in a Japanese population." (PMID 36398696, 2022). "SOCS2 partake in the pathogenesis of ovarian cancer, acromegaly associated colonic polyps, osteoarthritis and type 2 diabetes." (PMID 34349769, 2021). "For example, circRNA hsa_circ_0005567 promotes M2 macrophage polarization by sponging hsa-miR-492 and inducing suppressor of cytokine signaling 2 (SOCS2) expression in osteoarthritis." (PMID 39451243, 2024). "A recent study has also suggested the crucial role of circ_0005567 in inhibiting chondrocyte apoptosis and the progression of osteoarthritis by promoting M2 polarization via the miR-492/SOCS2 signaling axis." (PMID 37035757, 2023). "Hsa_circ_0005567 overexpression promoted M2 macrophage polarization by binding to the miR-492/SOCS2 axis to reduce chondrocyte apoptosis, which could inhibit the progression of osteoarthritis." (PMID 37298501, 2023).
ovarian carcinoma (7 papers, 2015 to 2023). A malignant neoplasm originating from the surface ovarian epithelium. "SOCS2, encoding the suppressor of cytokine signaling protein, is frequently hypermethylated in primary ovarian cancer." (PMID 25965583, 2015). "For example, although hypermethylation of SOCS2 CpG islands was detected in 14% of ovarian cancer patients, our studies here revealed that oncogenic N-Ras has minimal impact on DNA methylation of the Socs2 promoter." (PMID 35352806, 2022). "The transection of miR-101 could remarkably downregulate SOCS2 and thus inhibit the invasion and metastasis of ovarian cancer cells." (PMID 35634311, 2022). "Because gene expression can be regulated by methylation of the promoters or enhancer elements of the gene, and hypermethylation of SOCS2 CpG islands was detected in 14% of ovarian cancer patients, we hypothesized that N-RasG12D may suppress Socs2 expression by changing methylation of Socs2 promoter." (PMID 35352806, 2022). "However, in ovarian cancer, miR-101 was reduced while SOCS2 gene expression increased." (PMID 35634311, 2022).
Insulin resistance (6 papers, 2008 to 2025). Increased resistance towards insulin, that is, diminished effectiveness of insulin in reducing blood glucose levels. "In experiments with SOCS2-deficient mice, a high-fat diet resulted in impaired glucose tolerance and insulin resistance, while SOCS2 overexpression improved glucose tolerance and insulin sensitivity." (PMID 40362828, 2025). "SOCS2 is thought to be negatively associated with enhanced TG secretion from the liver and insulin resistance, while CPT1 plays an important role in enhancing fatty acid oxidation." (PMID 32405407, 2020). "Considering inflammation and apoptosis plays a significant role during NASH 2, 3, 5, and SOCS2 can also inhibit insulin resistance 12, we think that SOCS2 in macrophages may play a major function, as an suppressor, for NASH progression and it in hepatocytes play a secondary role." (PMID 34803490, 2021). "SOCS2 mitigates the adverse effects of proinflammatory cytokines and down-regulates GHR signaling, which can exacerbate insulin resistance by promoting hepatic glucose production." (PMID 40362828, 2025).
Obesity (6 papers, 2008 to 2025). Accumulation of substantial excess body fat. "However, high‐fat diet‐fed SOCS2−/− mice exhibited higher insulin sensitivity and lower cytokine secretion, but adiposity increased, with both M1 macrophages and M2 macrophages augmenting, suggesting that SOCS2 plays a different modulator in the regulation of obesity‐induced chronic inflammation." (PMID 40045164, 2025).
viral infection (6 papers, 2018 to 2026). "Unlike other SOCS members, the role of SOCS2 in viral infection remains poorly understood." (PMID 42188169, 2026).
myocardial ischemia (5 papers, 2020 to 2022). A disorder of cardiac function caused by insufficient blood flow to the muscle tissue of the heart. "HIF1A-AS1 contributes to ventricular remodeling after myocardial ischemia/reperfusion injury by adsorption of microRNA-204, regulating SOCS2 expression." (PMID 35328496, 2022). "The lncRNA HIF1A-AS1 (HIF1A Antisense RNA 1) mediates the expression of SOCS2 (suppressor of cytokine signaling 2) by miR-204 to encourage ventricular remodeling followed by myocardial ischemia/reperfusion injury." (PMID 35246252, 2022). "have discovered that the reduction of SOCS2 protected cardiomyocytes from apoptosis that induced by myocardial ischemia/reperfusion injury." (PMID 33228663, 2020).
parasitemia (5 papers, 2013 to 2021). "In comparison, SOCS2−/− mice showed reduced parasitemia and decreased IFNγ and TNFα following T. cruzi infection, which was associated with increased generation of Treg cells but reduced memory T (Tm) cells." (PMID 34604264, 2021). "Studies on mice infected with Tripanozoma cruzi have shown that expression of SOCS2 facilitates inflammatory and immune responses to prevent myocardial dysfunction but increases parasitemia." (PMID 31615414, 2019). "In the cerebral malaria model, SOCS2−/− mice display increased parasitemia and reduced Treg cell infiltration in the late phase, an effect associated with increased numbers of Th1 and Th17 cells and elevated cytokine levels." (PMID 31949423, 2019). "In a mouse model of cerebral malaria SOCS2−/− mice initially showed reduced parasitemia, however at late stages they showed increased parasitemia associated with increased Th1 and Th17 cells and pro-inflammatory cytokines such as IL-6 and IL-17 with decreased Treg cell activation." (PMID 34604264, 2021).
Sepsis (5 papers, 2007 to 2025). Sepsis is defined as life-threatening organ dysfunction caused by a dysregulated host response to infection. "LPS upregulates miR-208a-5p in sepsis, which has been shown to activate the NF-κB/HIF-1α axis mediated by SOCS2, causing mitochondrial swelling and ultimately leading to cardiomyocyte apoptosis." (PMID 40041174, 2025). "CIS was increased in sepsis by EN and SOCS-2 in sham operation by PN, whereas SOCS-3 was increased with PN after CLP and decreased with PN after sham operation." (PMID 17634149, 2007). "In a sepsis-induced mouse model of myocardial apoptosis, the downregulation of miR-208 improved mitochondrial swelling and cell apoptosis by targeting activation of the suppressor of cytokine signaling 2 (SOCS2)." (PMID 34122082, 2021). "In animals with sepsis, the CIS expression was increased by EN, and SOCS-2 expression was greater in sham-operated animals than septic animals given PN." (PMID 17634149, 2007). "As seen in the prior study, however, SOCS-2 expression was not affected by sepsis." (PMID 17634149, 2007). "• Sepsis and the route of nutrition influence mRNA of SOCS proteins, CIS and SOCS-2, whereas SOCS-3 mRNA is increased in sepsis independent of nutrition." (PMID 17634149, 2007).
steatosis (5 papers, 2021 to 2025). Increased lipid within the cytoplasm of cells. "Additionally, mice with diet-induced obesity/steatosis exhibit reduced circulating GH levels, where GH treatment or elevation in endogenous GH or GH-signaling due to the loss of SOCS2 decreases diet-induced steatosis." (PMID 34685512, 2021). "Moreover, GFP suppressed pro-inflammatory and lipogenic genes (acetyl-CoA carboxylase (Acc), Tnfα, Suppressor of cytokine signaling 2 (Socs2)) and favorably reshaped gut microbiota, collectively mitigating steatosis and hepatic injury." (PMID 41302443, 2025). "Consistent with our RNA-Seq result, SOCS2 mRNA and protein level were considerably lower in individuals with simple steatosis or NASH than in the nonsteatotic controls, and the NASH group had markedly lower SOCS2 expression than the simple steatosis group (P<0.001)." (PMID 34803490, 2021). "However, the results obtained for other genes negatively associated with serum ferritin in this cohort with steatosis seemed counterintuitive (GYS2, SEC24B, SOCS2)." (PMID 33962692, 2021). "Modulated the expression of specific gene related to lipid synthesis and conversion, CYP4A1, ACC, TNF-α, SOCS2 and CYP7A1; reduced hepatocyte steatosis and liver cell injury." (PMID 36671814, 2023). "NASH model showed that SOCS2 overexpression alleviates the development of NASH compared with the controls, as evidence by a reduced whole body, increased hepatocyte vacuolation, steatosis, and fibrosis." (PMID 34803490, 2021). "Next, to determine the clinical relevance of SOCS2 in NASH, we examined its expression in the liver tissue macrophage samples of human subjects without steatosis, with simple steatosis and with NASH." (PMID 34803490, 2021).
asthma (4 papers, 2019 to 2022). "However, deficiency of SOCS2 was reported to enhance Th2 differentiation in a murine model of allergy and asthma, in which STAT6 and STAT5 were activated, whereas STAT3, which is crucial for Th17 polarization was not." (PMID 31949423, 2019). "For example, the gene which was ranked third, Socs2, regulates the T helper cell type 2 (Th2) and the pathogenesis of type 2 immune responses such as asthma." (PMID 35332165, 2022). "In mice, loss of SOCS2 biases towards CD4+ Th2 differentiation, suggesting patients with allergic diseases such as atopic dermatitis and asthma may benefit from enhanced SOCS2 expression or activity." (PMID 34857742, 2021).
colitis (4 papers, 2017 to 2020). Inflammation of the colon. "SOCS2−/− mice showed increased GH sensitivity during the active colitis and recovery periods, and this is associated with increased intestinal epithelial turnover and less collagen deposition at the recovery phase." (PMID 32349250, 2020). "In conclusion, our results demonstrate that deletion of the SOCS2 protein causes exacerbated colonic inflammation during colitis but is associated with decreased fibrosis at recovery measured by levels of α-SMA and collagen deposition." (PMID 32349250, 2020). "Using a SOCS2−/− mice model of colitis we show that SOCS2-deficiency is pro-inflammatory and negatively correlates with NDR1 and nuclear p65 levels." (PMID 28216640, 2017). "During induction of colitis (Days 5–10), SOCS2−/− mice had significant weight reduction compared to the wild type." (PMID 32349250, 2020). "During induction of colitis and recovery, SOCS2−/− mice showed GH sensitivity compared to the wild-type mice." (PMID 32349250, 2020). "SOCS2−/− mice showed higher disease activity during colitis with increased mRNA expression of the pro-inflammatory cytokines nitric oxide synthase 2 (NOS2) and interleukin 1 β (IL1-β)." (PMID 32349250, 2020). "Deletion of SOCS2 execrates the inflammatory pathways, which increase disease activity during colitis." (PMID 32349250, 2020). "SOCS2−/− mice showed higher disease activity during induction of colitis and recovery compared to the wild-type littermates." (PMID 32349250, 2020). "Expression of TGF-β RII was significantly lower in SOCS2−/− mice prior and after induction of colitis." (PMID 32349250, 2020). "In the present study, we investigated the effect of cellular sensitivity to GH via suppressor of cytokine signaling 2 (SOCS2) deletion on colitis and recovery." (PMID 32349250, 2020). "Here we demonstrated, via deletion of SOCS2, the effect of increased GH sensitivity on disease pathogenesis of colitis." (PMID 32349250, 2020). "TGF-β RIII protein levels were lower in SOCS2−/− mice prior and after induction of colitis." (PMID 32349250, 2020). "These striking data indicate that the level of bone loss in DSS colitis is influenced by Socs2 expression and furthermore suggest that the absence of SOCS2 is partially protective against the bone loss that is typical of IBD." (PMID 29343614, 2018). "To directly examine this, we studied bones from a mouse model of IBD using dextran sodium sulfate (DSS)-induced colitis and investigated the potential of ablating the expression of Socs2 to endogenously elevate GH and IGF-1 function, and correct the bone loss observed in murine colitis." (PMID 29343614, 2018). "In this study, we aim to explore the effect of increased GH sensitivity via SOCS2 deletion on the inflammatory process and recovery from colonic inflammation using an established DSS-induced colitis mouse model." (PMID 32349250, 2020).
depression (4 papers, 2010 to 2025). "Socs2 has been shown to promote neurogenesis and enhance neurite outgrowth, a function relevant to depression: hippocampal volume is often reduced in depressed patients, and antidepressants may alleviate depression by promoting neurogenesis." (PMID 21206921, 2010). "Over-expression of miR-9-5p in MDD mice enhanced M1 polarization and increased depression-like behavior by suppressing SOCS2 expression and activating the JAK/STAT3 pathways; conversely, miR-9-5p inhibition alleviated depression in MDD mice." (PMID 36613914, 2022).
diabetic nephropathy (4 papers, 2017 to 2025). "Studies in diabetic nephropathy models have identified SOCS2 as a target gene of miR‐144, which in turn can be targeted by cancer susceptibility candidate 2 (CASC2)." (PMID 40067024, 2025). "Overexpression of CASC2 mitigated cell apoptosis and the release of inflammatory factors such as IL‐1β, IL‐6, and TNF‐α through the miR‐144/SOCS2 axis, slowing the progression of diabetic nephropathy." (PMID 40067024, 2025). "The suppressor of cytokine signaling 2 (SOCS2) is a key regulator of the inflammatory response and is implicated in the pathogenesis of diabetic nephropathy." (PMID 40067024, 2025). "Suppressor of cytokine signaling 2 (SOCS2) was reported to be involved in the development of Diabetic Nephropathy (DN)." (PMID 29207635, 2017). "Although the role of SOCS2 in the regulation of oxidative stress in diabetic nephropathy has not been fully elucidated, SOCS2 has been revealed to modulate ROS formation in hepatocytes." (PMID 35207562, 2022).
epilepsy (4 papers, 2008 to 2024). A brain disorder characterized by episodes of abnormally increased neuronal discharge resulting in transient episodes of sensory or motor neurological dysfunction, or psychic dysfunction. "suggest that circHivep2 regulates microglia activation in the progression of epilepsy by interfering with miR‐181a‐5p to promote suppressor of cytokine signaling 2 (SOCS2) expression." (PMID 38676299, 2024). "Our results suggest that circHivep2 regulates microglia activation in the progression of epilepsy by interfering with miR‐181a‐5p to promote SOCS2 expression, indicating that circHivep2 may serve as a therapeutic tool to prevent the development of epilepsy." (PMID 33002329, 2020). "CircHivep2 interacts with miR-181a-5p to upregulate the expression of suppressor of cytokine signaling 2 (SOCS2), promote microglial activation, and inhibit the expression of pro-inflammatory factors in epilepsy." (PMID 36979506, 2023).
type 2 diabetes (4 papers, 2011 to 2023). "Already, several polymorphisms of the SOCS2 gene has been identified in humans, one linked to height while the other one is linked to type 2 diabetes." (PMID 21980433, 2011). "The impact analysis also revealed the enrichment of the “Type II diabetes mellitus” pathway resulting from the upregulation of MAPK10 and IRS2 and the downregulation of CACNA1A and SOCS2, a signature that may upregulate the insulin receptor (INSR), PI3K, and insulin resistance." (PMID 36835058, 2023).